TGM2 (transglutaminase 2)
Diseases named in the same sentence as TGM2 in open-access papers (continued):
Sharing a sentence is not in itself a finding about the gene and the disease.
esophageal adenocarcinoma (1 paper, 2022). A malignant tumor with glandular differentiation arising predominantly from Barrett mucosa in the lower third of the esophagus. "TGM2 is overexpressed in esophageal adenocarcinoma and attaches to tumor staging." (PMID 35669563, 2022).
gallbladder cancer (1 paper, 2025). "In addition, a single‐cell study on immune remodeling in gallbladder cancer found that senescent Tgm2+ fibroblasts altered the tumor microenvironment through SASP, resisted immunotherapy, and promoted tumor migration." (PMID 39749582, 2025).
head and neck squamous cell carcinoma (1 paper, 2019). A squamous cell carcinoma that arises from any of the following anatomic sites: lip and oral cavity, nasal cavity, paranasal sinuses, pharynx, larynx, and salivary glands. "Here, the same tendency in expression changes of TGM2, MMP2, CLDN7, HOXB7, and LCP1 can be found in different cancer types, including cervical and head and neck squamous cell carcinoma." (PMID 30918060, 2019).
hyperlipidemia (1 paper, 2022). "Especially, tryptophan and glycerophospholipid metabolism, and related targets such as TGM2, BCHE and PLA2G2A should be paid more attention, since the regulation of leonurine on these two pathways was also observed in our previous metabolomics study of clinical hyperlipidemia patients." (PMID 36072867, 2022).
Hyperphosphataemia (1 paper, 2021). "Hyperphosphataemia is correlated with increased renal transglutaminase-2 (TG-2) expression in cats, which is an activator of the TGF-β1 signalling pathway." (PMID 33375963, 2021).
ichthyosis (1 paper, 2021). Disorders of cornification that are characterized by visible scaling and/or hyperkeratosis of most or all of the skin. "Tgm1 defects have been associated with aberrant cornification and ichthyosis, whereas Tgm2 acts in many tissues and stabilizes extracellular matrices." (PMID 34956208, 2021).
intracranial aneurysms (1 paper, 2022). "Several of these target genes have been reported to be closely related to the formation, growth and rupture of intracranial aneurysms, including transglutaminase 2 (TGM2), epiregulin (EREG), endothelin-1 (EDN1) and alpha 1 type IV collagen (COL4A1)." (PMID 35242102, 2022).
ischemic stroke (1 paper, 2023). A stroke disorder caused by obstruction of blood flow to the brain, due to thrombotic (local blood clot formation) or embolic (due to a blood clot or other material traveling from another site) event. "TGM2 plays a prosurvival role in injured liver as well as in ischemic stroke, while TGM2 accumulation results in cell death in hepatocytes, neuroglastoma cells, and neurons." (PMID 36831225, 2023).
kidney cancer (1 paper, 2018). Primary or metastatic malignant neoplasm involving the kidney. "TGM2 expression levels and clinical information about kidney cancer patients were obtained from cBioPortal." (PMID 30463244, 2018).
Lassa fever (1 paper, 2021). A viral hemorrhagic fever that is caused by the Lassa virus, which is transmitted by contact with infected rodents; it is characterized by fever, headache, malaise, myalgia, and hearing loss. "Genes involved in extracellular matrix and cell-adhesion were also modulated, particularly during fatal Lassa fever (NID1, TIMP3, ITGA11, TGM2, MMP8/9, OLFM4, PCDH20, and CADM3), as well as some others involved in coagulation (SERPIN, TFPI2) and apoptosis (CLU, BCL2L14)." (PMID 33398113, 2021).
myopia (1 paper, 2023). "Further studies should investigate the interaction between TGM-2 and muscarinic receptors, as well as the changes in other extracellular matrix genes associated with growth during the development of myopia." (PMID 37509081, 2023). "Our results evidence the change in the regulation of TGM-2, an extracellular matrix-associated cross-linking enzyme, in experimental myopia in the mouse sclera." (PMID 37509081, 2023). "Further research is needed to gain a deeper understanding of the molecular mechanisms underlying TGM-2’s involvement in myopia development." (PMID 37509081, 2023). "If TGM-2 or its associated molecules are found to contribute to scleral elongation in experimental myopia, they could serve as the basis for novel pharmacological interventions for human myopia." (PMID 37509081, 2023). "Overall, our data suggest that TGM-2 plays an indispensable role in the development of myopia in this animal model by regulating axial elongation and scleral growth." (PMID 37509081, 2023). "The study found that TGM-2 mediates these processes, suggesting its potential role in the development of myopia." (PMID 37509081, 2023). "Our goal is to reduce the side effects associated with atropine (the current standard of care for school myopes) by elucidating the molecular mechanism of transglutaminase-2 and muscarinic cholinergic receptors in experimental myopia." (PMID 37509081, 2023). "In this study, we found that the homozygous TGM2-deleted gene in mice protected against the development of myopia by slowing down the elongation of the eye." (PMID 37509081, 2023). "The up-regulation of TGM-2 in the scleral tissues of myopic eyes suggests its potential as a therapeutic target for controlling myopia progression." (PMID 37509081, 2023). "Investigating the signaling pathways and interactions that regulate TGM-2 activity in the context of myopia could provide valuable insights into potential therapeutic interventions." (PMID 37509081, 2023). "In conclusion, targeting TGM-2 may have a beneficial effect regarding myopia, and this may also be at least partially be the mechanism of anti-muscarinic drugs in myopia." (PMID 37509081, 2023). "Based on these findings, we hypothesize that drugs targeting TGM-2 and/or mAChR2/3 could be beneficial in reducing myopia progression while overcoming the side effects of atropine." (PMID 37509081, 2023). "Thus, we recommend investigating the central role of TGM-2 in the development of experimental myopia in mice by inducing myopia in TGM-2-deleted mice and mice treated with TGM inhibitors." (PMID 37509081, 2023). "Additionally, the study found that the pharmacological blockade of muscarinic receptors also slowed the progression of myopia in mice, and this effect was accompanied by a decrease in TGM-2 enzyme expression." (PMID 37509081, 2023). "Furthermore, we examined the role of TGM-2 in muscarinic receptor signaling by using TGM inhibitors in mice with deleted muscarinic receptor subtypes prior to inducing myopia." (PMID 37509081, 2023). "TGM-2 appears to be involved in processes such as fibroblast proliferation and migration, as well as extracellular matrix remodeling, which are crucial for the structural changes observed in myopia." (PMID 37509081, 2023). "Furthermore, the present study demonstrated that TGM-2 interacts directly with muscarinic receptors and other extracellular matrix genes to control changes in scleral growth that occur during myopia development." (PMID 37509081, 2023). "Furthermore, TGM-2 was found to interact with mAChRs and other extracellular matrix genes to regulate scleral growth-related changes during myopia development." (PMID 37509081, 2023). "Thus, we hypothesize that the regulation of TGM-2 is necessary for the growth of the sclera in experimental myopia." (PMID 37509081, 2023).
myopia (continued). "Additionally, exploring the effects of TGM-2 inhibition or modulation in animal models and clinical trials could offer a better understanding of its potential as a therapeutic target for myopia management." (PMID 37509081, 2023). "The study demonstrated that TGM-2 is involved in the development of axial elongation, further supporting the idea that TGM-2 plays a role in myopia progression." (PMID 37509081, 2023). "They observed the up-regulation of TGM-2 and collagen III in the scleral tissues, indicating their possible involvement in myopia development." (PMID 37509081, 2023). "Additionally, considering the results reported in the present study that pertain to the effects of TGM-2 inhibition or modulation in other animal models and subsequent clinical trials could offer a better understanding of its potential as a therapeutic target for myopia management." (PMID 37509081, 2023). "In a mouse model of myopia induced by wearing a negative lens on one eye, we observed that scleral fibroblasts increased staining for TGM2 protein, and TGM2 RNA levels were higher in the myopic eye than in the control eye." (PMID 37509081, 2023). "In a mouse model of myopia induced by the wearing of a negative lens on one eye, we observed high levels of TGM-2 protein staining in the sclera and elevated TGM-2 transcription levels and protein levels in myopic sclera compared to the control sclera (normalized to the GAPDH)." (PMID 37509081, 2023).
nasopharyngeal squamous cell carcinoma (1 paper, 2024). A squamous cell carcinoma that arises from the nasopharynx. "It was previously reported that transglutaminase-2 mediated chemotherapy resistance in nasopharyngeal squamous cell carcinoma cells, thus promoting cancer progression." (PMID 38286865, 2024).
non-alcoholic fatty liver disease (1 paper, 2025). "A selective oral transglutaminase 2 inhibitor called ZED-1227 is being developed to treat CeD and non-alcoholic fatty liver disease (NAFLD)." (PMID 40281872, 2025).
Osteochondroma (1 paper, 2020). A common, benign cartiliginous neoplasm arising from the metaphysis of bone. "RARγ target genes, TGM2 and CYP26B were up-regulated in osteochondromas." (PMID 32294904, 2020).
ovarian serous cystadenocarcinoma (1 paper, 2020). A malignant serous cystic epithelial neoplasm arising from the ovary. "Besides, according to the “Ovarian Serous Cystadenocarcinoma (TCGA)” study and using the tools from cBioportal, up-regulation of MIEN1, TGM2 or ZN428 in samples from these patients is correlated to poorer survival outcomes." (PMID 32867128, 2020).
scleroderma (1 paper, 2025). Scleroderma is a rare autoimmune connective tissue disorder characterized by abnormal hardening of the skin and, sometimes, other organs. "Our study has shown that TGM2 is highly expressed in scleroderma skin where it is widely distributed and associated with many cell types." (PMID 39800950, 2025). "Investigations encompassing both skin sections and primary fibroblasts obtained from patients with scleroderma, alongside the bleomycin‐induced skin injury model of sclerosis, sought to unravel the expression and activity of TGM2." (PMID 39800950, 2025). "TGM2 staining was observed in all skin compartments (epidermis, dermis, vascular, and inflammatory infiltrates) in both HC and scleroderma samples." (PMID 39800950, 2025). "HC and scleroderma fibroblasts were cultured alone and in the presence of increasing concentrations of TGM2 inhibitory antibody." (PMID 39800950, 2025). "TGM2 was found to be widely expressed in both control and scleroderma skin samples, as well as in cultured fibroblasts." (PMID 39800950, 2025). "This study aimed to investigate the expression and function of transglutaminase 2 (TGM2) in scleroderma skin and experimentally induced dermal fibrosis to determine its potential role and therapeutic implications." (PMID 39800950, 2025). "TGM2 expression in keratinocytes was evenly distributed in both HC and scleroderma tissue, with a slight decrease in NL samples and in lcSSc." (PMID 39800950, 2025). "These revealed that TGM2 is not only expressed by both control and scleroderma fibroblasts but also exhibits heightened expression levels in scleroderma, thus shedding light on a potentially key role in the pathogenesis of this complex disorder." (PMID 39800950, 2025). "Vascular and perivascular staining levels of TGM2 remained unchanged across the scleroderma disease spectrum." (PMID 39800950, 2025). "Our data suggest that TGM2 plays a role in skin fibrosis in scleroderma involving interactions between TGM2 and TGF‐β1 in dermal fibroblasts leading to enhanced ECM production and a profibrotic phenotype." (PMID 39800950, 2025). "Scleroderma fibroblasts exhibited elevated TGM2 expression, which correlated with increased expression of fibrosis markers (Col‐1, αSMA, and CCN2)." (PMID 39800950, 2025). "TGF‐β bioactivity and Smad2/3 phosphorylation were also reduced in TGM2 inhibited scleroderma cells." (PMID 39800950, 2025). "Here we deepen our understanding of TGM2 in the context of scleroderma." (PMID 39800950, 2025). "The availability of a human specific monoclonal antibody for TGM228 provides extra impetus toward the potential use of TGM2 blockade in scleroderma and would significantly add to the increasing number of antifibrotic therapies available or currently under investigation for this scleroderma." (PMID 39800950, 2025). "Our study did not specifically phenotype the TGM2 expressing cells in the dermis, but suggest that in scleroderma several cell types are contributing to TGM2 expression and release, including fibroblasts." (PMID 39800950, 2025). "Nonetheless, together these data provide strong evidence for the involvement of TGM2 in dermal fibrosis in scleroderma through the regulation of TGF‐β and the reciprocal modulation by TGM2 of TGF‐β functional activity, thus revealing that there are several ways by which TGM2 can promote fibrosis." (PMID 39800950, 2025). "Although this current study did not assess scleroderma lung, TGM2 is expressed by pulmonary fibroblasts." (PMID 39800950, 2025).
thyroid cancer (1 paper, 2024). "To uncover the most distinct genes in different thyroid cancer subtypes, we screened BCL2, BHLHE40, MICAL2, TGM2, and TPO by comparing each pair of existing subtypes." (PMID 39872516, 2024).
thyroid medullary cancer (1 paper, 2025). "Furthermore, using Tgm2-KO mice and orthotopically and i.v. inoculated preclinical models of NEPC, SCLC, and thyroid medullary cancer, our results imply that the crosstalk between H3Q5ser and H3cit was of functional importance in NET formation and cancer metastasis." (PMID 39903533, 2025).
triple-negative breast carcinoma (1 paper, 2022). An invasive breast carcinoma which is negative for expression of estrogen receptor (ER), progesterone receptor (PR), and human epidermal growth factor receptor 2 (HER2). "This relationship between TGM2 expression and distant metastasis-free survival was even more robust in triple negative breast cancer (TNBC) patients (Győrffy, 2021)." (PMID 36475545, 2022).
uveitis (1 paper, 2020). An inflammatory process affecting a part of or the entire uvea. "This is contradictory to a study on endotoxin-induced uveitis, in which the level of TGM2 was increased in aqueous humor." (PMID 32458144, 2020).
vitiligo (1 paper, 2022). Generalized well circumscribed patches of leukoderma that are generally distributed over symmetric body locations and is due to autoimmune destruction of melanocytes. "However, little is known about the function of A2M and TGM2 in vitiligo, which needs to be explored in the future." (PMID 35406685, 2022). "A2M and TGM2 were predicted to be the inhibitory upstream regulators of the DEARGs in vitiligo." (PMID 35406685, 2022). "Moreover, A2M and TGM2 upstream regulators were also found to be differentially expressed in vitiligo samples." (PMID 35406685, 2022). "Moreover, A2M and TGM2 were shown to be downregulated in vitiligo lesions from our RNA-seq dataset, which more favorably indicates that their decreased expression might subsequently cause the expression alterations of the downstream DEARGs." (PMID 35406685, 2022).
cancer (264 papers, 2005 to 2025). A tumor composed of atypical neoplastic, often pleomorphic cells that invade other tissues. "As a result, altered TGM2 function has been linked to a number of human diseases, including celiac disease, diabetes, inflammatory disease, tissue fibrosis, various cancers, and, as detailed below, NDDs." (PMID 39769187, 2024). "In cancer cells, TGM2 protein is associated with β1, β3, and β5 integrin, and TGM2 expression is positively correlated with the process of cell adhesion, migration, and invasion of the ECM." (PMID 37115802, 2023). "Aberrant expression of transglutaminase-2 (TG2), a mediator of calcium-dependent post-translational modifications via transamidation of proteins, has been implicated in the progression of cancer." (PMID 37160910, 2023). "Here, we found that high expression of FSCN1 and ITGA5 is associated with impaired survival in more than ten cancers, and high expression of TGM2 is also associated with poor prognosis in more than five cancers." (PMID 36978029, 2023). "Contrarily, the up-regulation of TGM2 expression/activity has been linked to a greater incidence of metastasis in various cancer entities." (PMID 36399280, 2022). "The expression of TGM2 was found to be upregulated in several types of cancer, which is associated with most of the highly aggressive forms of cancer." (PMID 35853996, 2022). "In fact, as shown in a recent paper describing the role of TGM2 in cancer, this gene is implicated in PDGF signalling, inflammation, integrin signalling, as well as angiogenesis, as we have found in our Network analysis." (PMID 34449674, 2021). "The multifunctional enzyme Transglutaminase 2 (TGM2), which harbors transamidation and GTPase activity, has been implicated in the development and progression of different types of human cancers." (PMID 34103685, 2021). "TGM2, a cross-linking enzyme, has been demonstrated to be tightly associated with chemosensitivity in diverse cancers." (PMID 33435987, 2021). "Transglutaminase 2 expression and activity have been implicated in the inflammatory processes and diseases, including cancer." (PMID 30736384, 2019). "Transglutaminase 2 present in the ECM supports the adhesion of cancer cells to the matrix, and cell surface TG2 is associated with integrins and mediates cell–matrix adhesion." (PMID 30691081, 2019). "Tgm2 encodes transglutaminase 2, which catalyzes the cross-linking of proteins, stabilizes the extracellular matrix, and is upregulated in fibrosis and cancer metastasis." (PMID 29242629, 2017). "We have demonstrated a compensatory increase in TGM2 in response to rapamycin treatment in various mTORC1-hyperactive cancer cells due to various tumor suppressor mutations." (PMID 26872016, 2016). "Herein, we found that rapamycin treatment promotes TGM2 expression in mTORC1-hyperactive cancer cells, including tsc1-/- and tsc2-/- MEFs, TSC2-deficient patient-derived cells, MCF-7 and 786-O cells." (PMID 26872016, 2016). "Increased expression of TGM2 is associated with drug resistance in cancer, due to activation of nuclear factor-kB (NF-kB) via cross-linking and polymerization of free I-kB by TGM2." (PMID 22458929, 2012). "This may be because the reduction in Glu intake caused by sh-TGM2 was compensated by exogenous Glu, alleviating the energy needs of cancer cells and resulting in a moderate decrease in P2RX7 activity." (PMID 41469519, 2025). "Conversely, TGM2 exhibited positive correlations with immunosuppressive cell populations, including M2 macrophages, cancer-associated fibroblasts (R = 0.365, P < 0.0001), hematopoietic stem cells (R = 0.469, P < 0.0001), and endothelial cells (R = 0.628, P < 0.0001)." (PMID 41050683, 2025). "Human transglutaminase 2 (TGase2) has various functions, including roles in various cellular processes such as apoptosis, development, differentiation, wound healing, and angiogenesis, and is linked to many diseases such as cancer." (PMID 32210142, 2020).